LEP (leptin)
Diseases named in the same sentence as LEP in open-access papers (continued):
Sharing a sentence is not in itself a finding about the gene and the disease.
primary aldosteronism (1 paper, 2024). An endocrine disorder characterized by excessive production of aldosterone by the adrenal glands. "Previously, we have shown an altered expression of different adipocytokines (leptin, adiponectin, resistin) both at circulating level and increased tissue expression in pathologies characterized by an increased cardiovascular risk (i.e., Primary Aldosteronism and Subclinical Cushing's Syndrome)." (PMID 38606379, 2024).
Primary amenorrhea (1 paper, 2013). "Recently, an interesting case has been reported of a young woman with CGL, undetectable leptin levels and primary amenorrhea who after treatment with leptin underwent menarche and adequate sexual maturation." (PMID 22851226, 2013).
primary progressive-MS (1 paper, 2013). "In controls, there were positive correlations between circulating leptin and resistin with TNF-α and IL-1β in subgroup analysis, the highest levels of TNF-α, IL-1β, hs-CRP, resistin and leptin were observed in primary progressive-MS (PP-MS) patients." (PMID 24098530, 2013).
prostate adenocarcinoma (1 paper, 2019). "This suggestion is reinforced by the fact that the expression of LEP, leptin receptor (LEPR) and its main downstream signaling genes (JAK2, STAT3) is reduced in prostate adenocarcinoma, suggesting that this system is involved in the mechanism of apoptosis defense in proliferating tumor cells." (PMID 31671654, 2019).
prostatic intraepithelial neoplasia (1 paper, 2025). "Obese mice that do not express leptin present an increase in periprostatic WAT, atrophy of the acini with epithelial changes indicative of prostatic intraepithelial neoplasia (PIN), an increase in markers of cell death (Caspase‐3) and inflammation (Interleukin‐6 and Tumor Necrosis Factor‐alpha)." (PMID 40195898, 2025).
psychosomatic disorders (1 paper, 2025). "This review first outlines how epigenetic dysregulation contributes to psychosomatic disorders through altered expression of genes such as GRM2, TRPA1, SLC6A4, NR3C1, leptin, BDNF, NAT15, HDAC4, PRKCA, RTN1, PRKG1, and HDAC7." (PMID 41439979, 2025).
pulpitis (1 paper, 2022). Inflammation of the dental pulp. "As a result, by regulating the expression of VEGF, leptin could play an important role in angiogenesis during pulpitis and REPs, similar to that which has already been described in other inflamed tissues and cancer." (PMID 35216099, 2022).
pyrexia (1 paper, 2021). "Adipose tissues appear to be involved in this mechanism since WAT secretes leptin, an adipokine essential to pyrexia in rodent by limiting heat loss at the tail level, and BAT make thermogenesis suspected for a long time to participate to pyrexia." (PMID 34437647, 2021). "Leptin is considered as a key mediator of pyrexia especially in mice by limiting body heat loss." (PMID 34437647, 2021). "In this line, leptin has been described as a major player in pyrexia in mice." (PMID 34437647, 2021). "Interestingly, we measured a decreased leptinemia as well as leptin secretion by scWAT in mice infected with bacteria as well as in mice treated with CL316,243, demonstrating that pyrexia in response to bacteria and thermogenesis are independent to leptin action." (PMID 34437647, 2021).
relapsing (1 paper, 2023). "Our current study showed, that besides leptin and fibronectin, also plasma UCHL1 could be a promising high-sensitive potential biomarker of relapsing–remitting MS, as it was the most useful in differentiating RRMS patients from healthy individuals." (PMID 36854961, 2023).
renal hypertension (1 paper, 2025). Hypertension caused by the kidney's hormonal response to narrowing or occlusion of the renal arteries. "Also, higher serum leptin levels have been connected to renal hypertension and subsequent glomerular harm." (PMID 40703753, 2025).
Retinal dysplasia (1 paper, 2017). Abnormal growth and differentiation, structure and appearance of the retina present from birth. "In summary, differential gene expression and cytological analyses of retinal dysplasia in adult Tg(flk1:RFP)is18/+ zebrafish predisposed to optic pathway tumors reveal that ectopic proliferation is associated with elevated expression of markers in the VEGF, Leptin, and mTOR pathways." (PMID 28192065, 2017).
retinal tumors (1 paper, 2017). "Compared to VEGF and Leptin signaling, mTOR activation may not be a factor in initiating inappropriate proliferation in the early dysplastic retina, but could contribute to the sustained growth of retinal tumors." (PMID 28192065, 2017).
Right ventricular hypertrophy (1 paper, 2019). In this case the right ventricle is more muscular than normal, causing a characteristic boot-shaped (coeur-en-sabot) appearance as seen on anterior- posterior chest x-rays. "In conclusion, ZDF rats show increased pulmonary arterial pressure, right ventricular hypertrophy, pulmonary arterial medial thickening and downregulated lung Bmpr2 despite leptin resistance." (PMID 30689673, 2019).
rosacea (1 paper, 2020). A chronic erythematous skin disorder that affects the face. "Leptin, adiponectin, resistin, SERPINE1 and visfatin were also detectable in the SGs of rosacea-involved skin, suggesting that through the secretion of these adipokines, SGs may contribute to the development of the characteristic inflammatory milieu in rosacea." (PMID 33260746, 2020).
secondary progressive MS (1 paper, 2025). "Similarly, serum leptin levels decreased in patients with secondary progressive MS (SPMS) who did not experience disease progression." (PMID 40019662, 2025).
sexual dysfunction (1 paper, 2020). Disturbances in sexual desire and the psychophysiologic changes that characterize the sexual response cycle and cause marked distress and interpersonal difficulty. "Firstly, hormonal and inflammatory responses induced by the fatty cell-secreted cytokine factors (i.e. TNF-alpha, IL-6and leptin) may contribute to the onset of sexual dysfunction." (PMID 32299459, 2020).
short bowel syndrome (1 paper, 2021). "In particular, in a rat model of short bowel syndrome, systemic infusion of leptin was found to enhance small intestine carbohydrate absorption and GLUT5 gene expression beyond the normal adaptive response." (PMID 33159578, 2021).
sick euthyroid syndrome (1 paper, 2014). "Available data support the concept of an inverse relationship between thyroid hormone and leptin and would explain the inverse relationship between waist circumference and sick euthyroid syndrome found in this study." (PMID 25574328, 2014).
skin infection (1 paper, 2022). An inflammatory process affecting the skin, caused by bacteria, viruses, parasites, or fungi. "AMPs are one of the most important immune defenses against skin infection, and given that microbial growth was reduced in frequency in leptin-treated explants, it is possible that there was an increased release of AMPs in our leptin-treated explants." (PMID 36093099, 2022).
Skin tags (1 paper, 2023). "Our results, showing the effect of OEO-PbH on reducing the number of newly forming vessels, and the limitation of leptin-induced angiogenesis represent relevant findings for the possible treatment of FP, commonly known as skin tags." (PMID 37513852, 2023).
SMA type 3 (1 paper, 2025). "The purpose of this study was to measure leptin and adiponectin levels in patients with SMA type 3 and explore their association with markers of insulin sensitivity." (PMID 40075777, 2025). "The aim of this study was to measure leptin and ApN levels in patients with SMA type 3 and explore their association with markers of insulin sensitivity." (PMID 40075777, 2025). "However, studies on leptin concentrations in adults with SMA type 3 are lacking." (PMID 40075777, 2025).
spinal muscular atrophy (1 paper, 2021). A motor neuron disease that affect the muscles, and characterized by muscle weakness and atrophy resulting from progressive degeneration and irreversible loss of the anterior horn cells in the spinal cord (i.e., lower motor neurons) and the brain stem nuclei. "Recent studies also suggest a link between leptin and degenerative conditions affecting motor neurons, as leptin levels are elevated in ALS patients and in children with spinal muscular atrophy." (PMID 33440796, 2021).
sterility (1 paper, 2016). "Leptin deficient female mice are infertile with low levels of gonadotropins and sex steroids and leptin treatment, but not weight loss, corrects sterility." (PMID 26875986, 2016).
syphilis (1 paper, 2019). A contagious bacterial infection caused by the spirochete Treponema pallidum. "Low Leptin and low IL27 were associated with incident syphilis whereas high Leptin and high IL27 were associated with treated infection (p-value: 0.009; OR, 16.5; 95% CI 2.25, 121.23)." (PMID 31186010, 2019). "We found that sub-groups of participants had different cytokine responses to incident syphilis: Some participants grouped into an Eotaxin–Rantes–Leptin network, whereas others grouped into a Mig-IL1ra-Trail-IL12p70 network." (PMID 31186010, 2019). "Leptin could have an important role in the immune response to syphilis, however it may also be elevated among our participants due to the treatment of syphilis with penicillin." (PMID 31186010, 2019).
systemic vasculitis (1 paper, 2012). "In the review of literature, we could find no study of the relationship of ghrelin and leptin with TA, and there was only one study investigating ghrelin levels in systemic vasculitis." (PMID 23259466, 2012).
T-cell immunodeficiency (1 paper, 2024). A broad classification of disorders that affect the cell-mediated aspect of the immune response. "Leptin, produced by adipose tissue proportionally to its mass, regulates the immune response: humans with mutations in the leptin gene have CD4+ T cell immunodeficiency and, therefore, an increased risk of infections." (PMID 38831236, 2024).
temporal lobe epilepsy (1 paper, 2019). A localization-related (focal) form of epilepsy characterized by recurrent seizures that arise from foci within the temporal lobe, most commonly from its mesial aspect. "However, several studies have reported that serum levels of leptin are significantly increased following amygdala electrical kindling (a model of temporal lobe epilepsy) in rats." (PMID 31749702, 2019).
thyroid tumor (1 paper, 2014). A benign or malignant neoplasm affecting the thyroid gland. "There was also a trend for serum leptin levels to be higher in multifocal primary thyroid tumors (p = 0.064)." (PMID 24867470, 2014).
thyrotoxicosis (1 paper, 2022). A hypermetabolic syndrome caused by the elevation of thyroid hormone levels in the serum. "Paradoxically, despite the widely reported increased appetite in thyrotoxicosis, in a longitudinal evaluation of hyperthyroid patients on treatment, leptin levels were higher and ghrelin levels were lower in the thyrotoxic state than in the euthyroid state." (PMID 35929907, 2022). "It is indeed quite a paradox that, while the anorexigenic hormone leptin is elevated in thyrotoxicosis and its orexigenic counterpart ghrelin is reduced, appetite is increased in thyrotoxicosis." (PMID 35929907, 2022). "In another study in patients with thyrotoxicosis, the ratio of observed leptin levels to expected leptin levels (based on BMI), expressed as a percentage, fell after treatment." (PMID 35929907, 2022). "Counterintuitively, the levels of leptin fell after treatment of thyrotoxicosis, despite the gain in fat mass." (PMID 35929907, 2022). "As leptin enhances energy expenditure, it is possible that high leptin in thyrotoxicosis may contribute to the increased energy production in thyrotoxicosis." (PMID 35929907, 2022). "As both FGF21 and leptin are elevated in thyrotoxicosis and as both are known to enhance energy expenditure, they may play an additive or synergistic role in promoting heat production in this condition." (PMID 35929907, 2022). "Thus, thyrotoxicosis is a useful model for understanding the role of the thyroid hormones in regulating weight, energy production, and appetite, either directly or through various mediators like leptin, ghrelin, and fibroblast growth factor 21 (FGF21)." (PMID 35929907, 2022). "High levels of thermogenic hormones, leptin, and FGF21 were observed in thyrotoxicosis and may be partly responsible for the excessive heat production typical of this condition." (PMID 35929907, 2022).
tubular adenoma (1 paper, 2014). A usually polypoid neoplasm arising from the glandular epithelium. "For each increase in leptin tertile, a participant was 2.0 (CI: 1.2–3.4) times more likely to have a tubular adenoma (p = 0.0115)." (PMID 24465801, 2014). "Participants with the highest concentrations of serum leptin were 3.8 (CI: 1.3–11.2) times more likely to have a tubular adenoma than those with serum leptin levels in the lowest tertile (p = 0.0134)." (PMID 24465801, 2014). "Serum leptin, IP-10 and TNF-α were significantly associated with tubular adenoma presence." (PMID 24465801, 2014).
upper tract urothelial carcinomas (1 paper, 2020). "Enhanced expression of leptin and its receptors has a positive association with the risk of breast, endometrial, colorectal, gastric, ovarian, and upper tract urothelial carcinomas." (PMID 32573960, 2020).
Urea (1 paper, 2022). "Urea was significantly positively correlated with leptin in all cats, and negatively correlated with I:G in cats once those with renal disease were removed." (PMID 35968003, 2022).
urolithiasis (1 paper, 2023). Stone(s) within the urinary tract. "Lower ghrelin values and higher leptin values than the control group characterized the group with urolithiasis." (PMID 36830821, 2023). "Our research has shown that leptin levels were higher and ghrelin levels were lower in people with urolithiasis than in the control group." (PMID 36830821, 2023). "The study’s strengths include that it was the first group of patients with urolithiasis to be examined for the levels of appetite hormones, such as ghrelin and leptin." (PMID 36830821, 2023). "For this reason, we decided to investigate what levels of ghrelin and leptin characterize the group with urolithiasis and whether they differ from those in healthy people." (PMID 36830821, 2023). "Due to the diet-dependent nature of the disease, which is urolithiasis, this topic should be looked at more closely, as research on appetite hormones, such as ghrelin and leptin, may positively affect the dietary aspects of the treatment of this disease." (PMID 36830821, 2023). "Despite demonstrating numerous relationships between leptin and UA, data about ghrelin and leptin levels in patients with urolithiasis are lacking in the existing literature." (PMID 36830821, 2023). "We also showed that, unlike leptin, ghrelin correlates with other outcomes such as IL-6, TNF-α, and UA only in the group of people with urolithiasis which may be helpful in further research on appetite hormones in patients with this condition." (PMID 36830821, 2023).
uterine tumours (1 paper, 2009). "However, weight-related increase in endometrial growth factors, cytokines (i.e., leptin, adiponectin) or transcription factors may be related to the development of uterine tumours." (PMID 19568239, 2009).
vascular hypertrophy (1 paper, 2015). "On the other hand, as opposed to leptin's generally detrimental effects on the cardiovascular system, adiponectin is a cardioprotective hormone that reduces left ventricular and vascular hypertrophy, oxidative stress, and inflammation." (PMID 26064110, 2015).
cancer (856 papers, 2002 to 2026). A tumor composed of atypical neoplastic, often pleomorphic cells that invade other tissues. "When elevated leptin levels are observed in cachectic patients, hyperleptinemia is not consistently observed despite significant weight loss in cancer patients." (PMID 40869331, 2025). "High leptin levels in obese patients increase the risk of developing cancer and increase the risk of cancer progression." (PMID 40387523, 2025). "Leptin-deficient ob/ob mice are obese mice that are suitable models for investigating the indirect causes of cancer and the development process of cancer." (PMID 40521210, 2025). "In our study, in a panel of 16 immunological factors, lower serum concentrations of PDGF-AB/BB and leptin were associated with cancer, and in the cystic fluid, cancerous tumors were associated with lower concentrations of sTIE-2, osteopontin, and leptin." (PMID 40940878, 2025). "In our study, lower leptin concentrations were associated with cancer occurrence, both in serum and in the cystic fluid, even though BMI was not significantly different between groups." (PMID 40940878, 2025). "This dysregulation is exacerbated in obesity-associated cancers, where both systemic inflammation and leptin resistance contribute to anorexia." (PMID 40704145, 2025). "Controversies exist regarding the specific adipokines (e.g., leptin versus adiponectin) driving cancer risk, as well as the role of AT-IR in different cancer types." (PMID 41153663, 2025). "Studies have shown that leptin expression is closely associated with the development of various cancers, such as breast cancer, CRC, and pancreatic cancer." (PMID 41267926, 2025). "Antagonizing role of adiponectin against leptin helps to explain how a decrease in adiponectin/leptin ratio increases the risk of cancers such as colorectal, prostate, hepatic, endometrial, and breast." (PMID 40304310, 2025). "Leptin, mainly released by white adipocytes, has been demonstrated to act as a significant cancer-associated adipokine in different types of malignancies, including colorectal, breast, liver, and ovarian cancer, and malignant melanoma." (PMID 40227577, 2025). "In FMC, remodeling of collagen fibers, cancer-associated fibroblasts (CAFs), regulatory T cells (Tregs) and elevated serum leptin have been associated with poor prognosis, whereas stromal cytotoxic T cells correlate with more favorable outcomes." (PMID 41150099, 2025). "In cancer patients, RCTs have reported that reductions in leptin are highly sensitive to weight loss." (PMID 40895542, 2025). "Increasing levels of leptin correlate with increased body fat percentage, which in turn increases the risk of biliary tract and other types of cancer." (PMID 40521210, 2025). "Cancer-associated fibroblasts express more leptin than normal lung fibroblasts, with high leptin and Ob-R expression in NSCLC cells as well." (PMID 41463203, 2025). "Taken together, RETA led to remarkable reductions in tumor progression that persisted even when the intervention was withdrawn and weight rebounded along with elevated adipokines and cytokines associated with cancer, namely leptin and IL-6." (PMID 40094000, 2025). "Increased leptin levels are associated with an increased risk of metabolic diseases, cardiovascular events, and some cancers." (PMID 39444577, 2024). "Obesity, a known risk factor for cancer, can indirectly affect cancer progression through its association with leptin." (PMID 38534979, 2024). "Oxidative stress from increased reactive oxygen species (ROS) and dysregulated adipokines, such as elevated leptin and reduced adiponectin, further contribute to cancer risk." (PMID 38999846, 2024). "We first measured the expression of genes involved in adipocyte differentiation (PPAR-γ, AP2, HSL, Adiponectin, Leptin), cancer-associated fibroblast (CAF) markers (LIF, FAP, α-SMA), and inflammation (IL-6, IL-8, IL-1β, CXCL-10, TNF-α)." (PMID 39072314, 2024).